TTR (transthyretin)
Diseases named in the same sentence as TTR in open-access papers (continued):
Sharing a sentence is not in itself a finding about the gene and the disease.
hereditary amyloidosis (79 papers, 2008 to 2026). Hereditary amyloidosis refers to a group of inherited conditions that make up one of the subtypes of amyloidosis. "Several studies have reported placental deposition of aggregates of Aβ and transthyretin, whose mutants cause the most common form of hereditary amyloidosis, in PE placentas." (PMID 41558820, 2026). "Most represented variants for TTR-related hereditary amyloidosis (n = 17, 0.43%) and RYR1-related malignant hyperthermia (n = 13, 0.33%)." (PMID 40332002, 2025). "Despite the importance of understanding TTR mutations, reports on familial amyloidosis associated with these mutations, particularly p.Ser43Asn, are relatively scarce." (PMID 40964530, 2025). "Hereditary amyloidosis results from gene mutations that alter the structure of proteins, such as transthyretin (TTR), subsequently leading to the deposition of amyloid fibrils, often involving the nervous system and heart." (PMID 40779499, 2025). "For patients with transthyretin (TTR)-related hereditary amyloidosis, genetic screening is required to determine the pathogenic mutation." (PMID 38638122, 2024). "Transthyretin-mediated hereditary amyloidosis (hATTR) is caused by a mutation in the gene coding for transthyretin (TTR), a protein produced by the liver that transports thyroxine and retinol in the plasma and cerebrospinal fluid." (PMID 38044945, 2023). "Hereditary amyloidosis is an autosomal dominant disease caused by a mutation in the transthyretin (TTR) gene that results in the accumulation of abnormal proteins such as amyloid fibrils in various organs." (PMID 37330968, 2023). "TTR encodes transthyretin, and pathogenic forms of transthyretin are known to cause hereditary amyloidosis." (PMID 38037155, 2023). "In cases related to hereditary amyloidosis caused by transthyretin, this therapy can be used to knock out TTR gene after just one application." (PMID 37720240, 2023). "Mutations in several genes are involved in hereditary amyloidosis and the most common one is the mutations in the transthyretin (TTR) gene." (PMID 35052837, 2022). "Genetic anticipation of serious symptoms, including an early age of onset and the rapid death of the subjects, was described for hereditary amyloidosis related to the Gly47Glu variant of the TTR gene." (PMID 36289657, 2022). "Transthyretin-related hereditary amyloidosis genetic testing revealed a rare c.251T > C variant p.(Phe84Ser)." (PMID 35795194, 2022). "Transthyretin (TTR)-related hereditary amyloidosis (ATTRv, v for variant) genetic testing revealed a rare c.251T > C variant p.(Phe84Ser)." (PMID 35795194, 2022). "Some studies allowed the identification of life-threatening risks, such as the mutations in the transthyretin (TTR) gene, which cause familial amyloidosis with severe cardiological and neurological dysfunctions." (PMID 34600567, 2021). "Hereditary amyloidosis associated with mutations in the transthyretin gene (hATTR) is a progressive devastating disease, with a fatal outcome occurring within 10years after onset." (PMID 33921571, 2021). "Hereditary amyloidosis associated with mutations in the transthyretin (TTR) gene (hATTR) is the most common form of genetic amyloidosis." (PMID 33921571, 2021). "Hereditary amyloidosis associated with transthyretin V30M (ATTRv V30M) is a rare and inherited multisystemic disease, with a variable presentation and a challenging diagnosis, follow-up and treatment." (PMID 33329366, 2020). "A rare case of hereditary amyloidosis associated with the TTR mutation (Pro24Ser) has been reported previously." (PMID 30553273, 2018). "The second type of ATTR is due to mutant TTR (ATTRm) causing familial amyloidosis; patients are generally born with a pathological mutation in the TTR gene, resulting in accelerated breakdown of TTR to amyloid." (PMID 32477799, 2018). "Since 2010, 214 genetic tests have been performed in search of mutations in the TTR gene with the suspicion of hereditary amyloidosis." (PMID 29970125, 2018).
hereditary amyloidosis (continued). "Hereditary transthyretin V30M amyloidosis (ATTRV30M) is an autosomal dominant disorder and is a very common form of hereditary amyloidosis caused by extracellular deposition of variants of transthyretin (TTR) in several tissues, including the eye." (PMID 30327725, 2018). "In this section the proposed method is applied to the transthyretin hereditary amyloidosis (hATTR), a severe autosomal dominant disorder caused by a mutation of the transthyretin (TTR) gene." (PMID 30252892, 2018). "The most common type of familial amyloidosis ismediated by mutation of transthyretin, especially Val30Met." (PMID 27992035, 2017). "Left ventricular longitudinal strain detected by two-dimensional speckletracking echocardiography is able to diagnose left ventricular dysfunctionin early stages of familial amyloidosis caused by transthyretin Val30Metmutation." (PMID 27992035, 2017). "Since the 1990s, liver transplantation has been used as a treatment for patients with TTR-related hereditary amyloidosis and as a result eliminating the main source of mutated TTR." (PMID 27050398, 2016). "Transthyretin-related hereditary amyloidosis is linked to more than 100 known heterozygous mutations in the gene coding for transthyretin (TTR), a plasma protein responsible for transporting thyroxine (T4) and holo-retinol-binding protein." (PMID 27050398, 2016). "For familial amyloidosis, the most frequent type seen on tertiary referral centers is caused by mutant transthyretin (TTR) deposition." (PMID 23617890, 2013). "Hereditary amyloidosis is caused the deposition of a mutant transthyretin protein synthesized by the liver." (PMID 20676282, 2009). "ATTRv is the most common hereditary amyloidosis globally, caused by mutations in the TTR protein." (PMID 39597824, 2024). "Point mutations of the transthyretin (TTR) gene are related with hereditary amyloidosis (hATTR)." (PMID 36289657, 2022). "AL (fibrils due to immunoglobulin light chain clonal production); AA (serum amyloid A congregation, secondary amyloidosis); ATTR (hereditary amyloidosis, genetic mutation of misfolding-prone protein (mainly transthyretin)); and ATTRwt (wild-type transthyretin misfolding)." (PMID 34830699, 2021). "Whereas wild-type TTR (TTRwt) is associated with acquired amyloidosis with mainly cardiac involvement (ATTRwt), different variants of TTR are the cause of hereditary amyloidosis involving the peripheral nervous system, autonomic nervous system, heart, eye, leptomeninges and vasculature of the brain." (PMID 33287192, 2020). "Hereditary amyloidosis refers to a wide spectrum of rare diseases with different causative mutations in the genes of various proteins including transthyretin, apolipoprotein AI and AII, gelsolin, lysozyme, cystatin C, fibrinogen Aα-chain, β2-microglobulin, apolipoprotein CII and CIII." (PMID 30665372, 2019). "Moreover, familial amyloidosis, caused by a transthyretin mutation occurs in approximately 1 of every 100,000 Caucasians in the U.S. and more commonly among African Americans (approximately 4% in that population)." (PMID 28877709, 2017). "Mutated transthyretin (TTR) is the most frequent cause in hereditary amyloidosis." (PMID 28272196, 2017). "Thus, new imaging techniques, as the STE, have been suggestedfor the evaluation of patients with CA.6-14 The aim of ourstudy was to determine the accuracy of LV longitudinal strain obtained bytwo-dimensional STE in a group of patient with familial amyloidosis caused by theVal30Met mutation of TTR." (PMID 27992035, 2017). "TTR-related hereditary amyloidosis has a significant cluster in northern Portugal, the largest worldwide." (PMID 40332002, 2025). "Companies such as Ionis Pharmaceuticals and Sarepta Therapeutics have developed several antisense therapies for Duchenne muscular dystrophy, transthyretin (TTR)-related hereditary amyloidosis, and spinal muscular atrophy." (PMID 39138523, 2024).
hereditary amyloidosis (continued). "Molecular and genetic testing can be performed in cases of hereditary amyloidosis (e.g., TTR, fibrinogen, lysozyme, apolipoproteins AI and AII, and gelsolin)." (PMID 39597824, 2024). "Since their development, Tegsedi (antisense therapy), Onpattro (RNAi), Amvuttra (RNAi), and Wainua (antisense therapy) have all been licensed for the treatment of TTR-related hereditary amyloidosis." (PMID 39138523, 2024). "Companies such as Alnylam developed RNAi therapies for TTR-related hereditary amyloidosis, porphyria, hyperoxaluria, etc.." (PMID 39138523, 2024). "For example, severe thrombocytopenia has been reported in patients with transthyretin-mediated hereditary amyloidosis treated with inotersen." (PMID 38044945, 2023). "These are Comirnaty® SARS-CoV-2 mRNA vaccine by BioNTech/Pfizer, mRNA-1273 SARS-CoV-2 mRNA vaccine by Moderna and Onpattro® transthyretin siRNA for hereditary amyloidosis by Alnylam." (PMID 35890195, 2022). "Patisiran, an RNA interference treatment agent, is used to treat transthyretin familial amyloidosis by specifically inhibiting transthyretin synthesis in the liver." (PMID 36189421, 2022). "Recent clinical data have shown the safety and efficacy of the gene editing therapy NTLA-2001 designed to treat hereditary amyloidosis through TTR gene knockdown in the liver." (PMID 36560658, 2022). "Hereditary or familial amyloidosis is another group including fibrinogen Aα chain, transthyretin (TTR), apolipoprotein A-I and apolipoprotein A-II, lysozyme, gelsolin and cystatin C." (PMID 34885818, 2021). "Hereditary amyloidosis is caused by GoF mutations in the ATTR gene leading to an abnormal, aggregation-prone TTR protein that is deposited in amyloid aggregates." (PMID 33324928, 2020). "Examples of recent clinical successes include nusinersen for spinal muscular atrophy, as well as inotersen for transthyretin (TTR) hereditary amyloidosis." (PMID 31336816, 2019). "Liver transplantation remains the most effective therapy for hereditary amyloidosis, by removing mutant TTR proteins." (PMID 20676282, 2009). "The pharmacological therapy for familial amyloidosis is limited, given the production of abnormal protein, Transthyretin, by the liver." (PMID 20676282, 2009). "It is important to note that lipid-encapsulated nanoparticles containing small interfering double-stranded RNA (siRNA) have been employed to target transthyretin (TTR) mRNA, leading to the degradation of TTR deposits in patients with TTR-mediated hereditary amyloidosis." (PMID 38139761, 2023). "Distinct datasets collect genetic and clinical information on SMA, CMT, familial amyloidosis of TTR-type, muscle glycogenoses, spinal and bulbar muscular atrophy, congenital myopathies, and muscular dystrophies (congenital, limb girdle, and facio-scapulo-humeral dystrophy types)." (PMID 34600567, 2021). "The genetic testing of proband’s relatives and the adoption of good practices to monitor even subtle clinical changes in asymptomatic carriers are particularly relevant for familial amyloidosis of TTR-type given the recent availability of effective innovative treatments." (PMID 34600567, 2021). "Many pathologic and non-pathologic TTR variations are already described including TTR variations with specific gene mutations that are associated with familial amyloidosis." (PMID 18682810, 2008). "Thus, suppressing the expression of transthyretin may be an effective way to treat hereditary amyloidosis." (PMID 35052837, 2022). "Importantly, a false negative scan may occur with certain TTR mutations, one of which is the S77Y mutation, which is a founder mutation among Yemenite Jewish descendants and the most common cause of familial amyloidosis in Israel." (PMID 36902083, 2023). "Transthyretin (TTR), a soluble secretory protein that is involved in familial amyloidosis, is not modified with N-glycans under normal conditions." (PMID 31810196, 2019).
hereditary amyloidosis (continued). "The two TTR antisera showed reaction only with amyloidof known TTR origin (i.e., Swedish familial amyloidosis and SSA) but not withamyloid of AA, AL, AMed, or Aβ nature, showing thatTTR-immunoreactivity is not a general feature of amyloid deposits." (PMID 18825272, 2008). "Apart from thrombus-associated amyloid deposition, four patients had systemic sporadic transthyretin-derived amyloid (ATTR) deposition, and none had a medical history of familial amyloidosis." (PMID 40429650, 2025).
malnutrition (48 papers, 2003 to 2025). Inadequate nutrition resulting from poor diet, malabsorption, or abnormal nutrient distribution. "The inflammatory process can lead to a decrease in TTR, which can be considered a nutritional risk factor, as inflamed patients commonly have greater difficulty in eating, leading to malnutrition." (PMID 39125329, 2024). "Similar to albumin, transthyretin is a marker of inflammation-related nutritional risk, a key component of malnutrition related to acute or chronic disease." (PMID 36891188, 2023). "An elevated ASA score, obesity, and malnutrition (low levels or plasma proteins, albumin and transthyretin) were also associated to MDR-Os infection." (PMID 35304900, 2022). "Nevertheless, plasma TTR is also negatively influenced by the acute-phase response due to inflammation, which is often associated with malnutrition." (PMID 36009453, 2022). "Transthyretin has the potential of early identification of patients at risk of malnutrition that elude detection and provide a good picture regarding the assessment of acute malnutrition." (PMID 28932602, 2017). "Using a biochemical marker such as transthyretin for the diagnosis of malnutrition allows many children to be evaluated for the risk of acute malnutrition regardless of underlying diagnosis of nutritional status." (PMID 28932602, 2017). "Due to its short half-life, transthyretin concentration is a good indicator of malnutrition risk and the effectiveness of nutritional treatment, but for the same reason, it is not possible to identify patients suffering from malnutrition solely by testing its plasma level." (PMID 40871731, 2025). "The underlying reasons for decreased transthyretin concentration may be associated with chronic inflammation, malnutrition, metabolic disorders, and other factors." (PMID 39478501, 2024). "Conversely, low TTR levels may be associated with an unfavorable outcome, which can often be attributed to malnutrition." (PMID 39125329, 2024). "Additionally, we also found that plasma levels of transthyretin – a biomarker for malnutrition was negatively associated with neuronal differentiation." (PMID 35794184, 2022). "Because we included in this study only those men who were otherwise healthy and free of serious disease, we believe that this trend was not likely to be just an artifact due to other known causes of changes in transthyretin, such as severe inflammatory disease and malnutrition." (PMID 30670838, 2020). "Reduced TTR serum concentrations are often associated with acute phase response, which may be due to inflammation, trauma or other disorders like malnutrition." (PMID 22630135, 2012). "Indeed, a plasma TTR concentration below 10 mg/dL has been associated with malnutrition." (PMID 36009453, 2022). "As an imbalance of redox status is a frequent complication in thyroid disease 17,35 as well as other diseases such as cancer and malnutrition, this association may direct towards a possible biochemical mechanism to regulate the interaction of TTR and T3 (thyroid hormones)." (PMID 25311081, 2015). "Reduced TTR has been reported to be associated with acute-phase response induced by inflammation, and TTR is also a malnutrition marker, suggesting nutritional disorders in severe cases." (PMID 35953823, 2022). "For instance, it has been long known that TTR levels are decreased in malnutrition, inflammation, and ovarian cancer." (PMID 34199897, 2021). "We defined severe malnutrition as severe hypoproteinemia: decrease of TTR to less than 15 mg/dl on the 5th day." (PMID 32689936, 2020). "Since TTR has a very short half-life of only 2–4 days, serum levels of TTR are routinely used as a marker of malnutrition and have appeared since the 1970s." (PMID 31316837, 2019). "TTR is a carrier protein that exhibits downregulation in ovarian cancer and several other diseases, such as liver disease, malnutrition, and acute inflammation." (PMID 29862288, 2018).